RNU6-620P (RNA, U6 small nuclear 620, pseudogene)
Gene: Small nuclear RNA gene on chromosome 5 (83,703,448 to 83,703,543, forward strand). Ensembl gene ENSG00000206744.
Homologues: Orthologues: chimpanzee U6 (99% identical), macaque U6 (94% identical), pig U6 (82% identical). Paralogues in human: RNU6-140P (90% identical), RNU6-16P (90% identical), RNU6-33P (90% identical), RNU6-480P (90% identical), RNU6-1 (89% identical), RNU6-1005P (89% identical), RNU6-1034P (89% identical), RNU6-116P (89% identical), RNU6-2 (89% identical), RNU6-39P (89% identical), RNU6-3P (89% identical), RNU6-4P (89% identical), and 1286 more.